IGF1R (insulin like growth factor 1 receptor)
Diseases named in the same sentence as IGF1R in open-access papers (continued):
Sharing a sentence is not in itself a finding about the gene and the disease.
tumor (continued). "Insulin-like growth factor-1 receptor (IGF-1R) also plays a very important role in tumorigenesis since it is involved in stimulating tumor growth and prevents apoptosis." (PMID 32906852, 2020). "Quantification for IGF1R/PCNA PLA signals was carried out by manually counting 100 tumor cells in at least three different randomly selected areas of the tumor." (PMID 32701997, 2020). "IGF-1R, which is strongly expressed in RMS and is associated with tumor initiation and progression, is considered a potential therapeutic target." (PMID 32630642, 2020). "The insulin-like growth factor 1 receptor (IGF-1R) is a transmembrane receptor tyrosine kinase overexpressed in neoplasms, having an anti-apoptotic effect through enhancement of survival and proliferation." (PMID 33198090, 2020). "For example, miR-140 suppresses tumor proliferation and metastasis by targeting insulin-like growth factor 1 receptor in NSCLC." (PMID 33098639, 2020). "The expressions of IGF1R and Ki-67 (a cell proliferation marker) in tumor samples collected from sh-circRNA group were reduced compared to the control mice." (PMID 32847606, 2020). "IGF1R positive CRCs tended to show an improved overall as well as tumor-specific survival, which missed significance (p = 0.076 and p = 0.076 respectively)." (PMID 32727431, 2020). "In order to achieve an improved comparability with the results of other study groups, we correlated IGF1R expression with survival by only evaluating the percentage of positively stained tumor cells." (PMID 32727431, 2020). "Therapies targeting IGF1R using IGF1R monoclonal antibody or IGF1R-selective inhibitor are under evaluation for their ability to repress tumor growth and metastasis, and increase the sensitivity of tumor cells to other biological therapies." (PMID 32847606, 2020). "Interactions between IGF-1R and E-cadherin have been previously reported in tumor biology where they are thought to regulate tumor invasion and in Madin Darby canine kidney cells." (PMID 32194500, 2020). "Second, we identified a novel protein biomarker pIGF-1R from pretreatment archival tumor specimens that appears to be predictive of ES tumor response to IGF-1R Ab-based therapy." (PMID 32630797, 2020). "The brain area covered by tumor cells became significantly, more than 2.5 times smaller in animals treated with the IGF1R inhibitor." (PMID 32534480, 2020). "Previously, it had been reported that IGF1R is reduced in tumour biopsy at the time of recurrence or resistance to tamoxifen and time to progression was significantly increased for IGF1R rich patients." (PMID 33198803, 2020). "Furin inactivation in mammary epithelial cells impaired proIGF1R and proIR processing and led to reduced amounts of cleaved IGF1R and IR in tumor mass of PyMT;KO mice." (PMID 32962246, 2020). "In this sense, CRC samples with cytoplasmic or membranous IGF1R expression in ≥10% of all tumor cells were classified as IGF1R positive." (PMID 32727431, 2020). "Both WB and immunofluorescence staining confirmed that activation of IGF1R in this tumor, mainly in tumor OPCs." (PMID 33173731, 2020). "Altogether, these findings suggest that a complex network between ER, GPER, and IGF-1R stimulates the tumor microenvironment and especially CAFs to facilitate metastatic spread." (PMID 33364239, 2020). "In order to further delineate the role of IGF1R in tumor OPCs, we reexamined the expression pattern of IGF1R in our scRNA‐seq dataset." (PMID 33173731, 2020). "KL seems to be an universal tumor suppressor in many different tumor entities owing to its inhibitory effect on pro-survival intracellular pathways including IGF-1R/PI3K/AKT or Wnt signaling." (PMID 33520985, 2020). "IGF1R/PCNA colocalization was more frequently increased in tumor cells than in adjacent normal, and more prominent in areas with dysplasia and invasion." (PMID 32701997, 2020).
tumor (continued). "Rodent studies found that reduced circulating IGF-1 levels led to decreased tumor development and that increased signaling through the IGF-1R signaling pathway promoted tumor growth." (PMID 33604295, 2020). "Both of them showed a high expression in CRC tumor tissues and cells, IR-A seemed to be expressed higher than IGF1R which made IR-A to have a higher ability than IGF1R to interact with IGF2." (PMID 33173015, 2020). "The authors provide evidence that inhibiting IGF1R in either mouse or human tumor epithelial cells increased reactive oxygen species production and activation of the endoplasmic reticulum stress response." (PMID 32391121, 2020). "Nevertheless, in the AXL-low-expressing tumor cells, through increased protein expression and phosphorylation of IGF-1R by osimertinib exposure (e.g., for 3 days), tolerance emerged via epigenetic modification." (PMID 32929081, 2020). "We propose the determination is due to different niches in embryo development and tumor malignancy which modulate the consequences of IGF-1R signaling." (PMID 33511137, 2020). "Ganitumab, a human monoclonal antibody to IGF-1R can enhance the therapeutic effect of platinum-based chemotherapy passing through the inhibition of the IGF-2-dependent tumor growth." (PMID 32498447, 2020). "Both IGF-1R inhibitor and mTOR inhibitor treatment significantly reduced the tumor growth in ES xenografts through inhibition of IGF-1R/PI3K/AKT/mTOR, and other signaling pathways, including MEK1/2, JAK/STAT3, TGF-β, and G-protein coupled receptors." (PMID 32754598, 2020). "Nuclear IGF-1R in cancers is positively correlated with tumor stage and presents higher protein levels in metastatic cancer." (PMID 33511137, 2020). "Adnectin, a VEGFR2 inhibitor, in combination with AT580Peg40, an IGF-1R inhibitor, reduced tumor growth by 83.4% in mice by normalizing the microvascular architecture via inhibition of autocrine VEGF-secretion and downregulation of IGF-1R." (PMID 32754598, 2020). "For example, inhibition of IGF1R represses tumor growth and induces apoptosis in different TNBC cell lines." (PMID 32962246, 2020). "Taken together, these results support the tumour suppressor function of Klotho and its modulation of IGF-1R signalling." (PMID 32585905, 2020). "Activation of the tyrosine kinase Src is responsible for tumor progression promoted by insulin-like growth factor 1 receptor (IGF-1R)." (PMID 31931755, 2020). "In the paediatric/young adult cohort there was evidence of improved survival for patients whose tumours had lower IGF-1R content (p = 0.011)." (PMID 31857716, 2020). "Taken together, inhibition of the IGF1R pathway has proved more promising in the FET oncogene associated tumors ES and DSRCT than in many other tumor types." (PMID 31426421, 2019). "Inhibitors to IGF-1R, which target hybrid receptors, also have undesirable metabolic effects, as well as induce resistance mechanisms by the tumor via up-regulation of IR." (PMID 31379747, 2019). "Their common target IGF1R is a proto-oncogene, which is highly expressed in several tumor cells, CDK4 and CDC25A are proto-oncogenes." (PMID 31540229, 2019). "Next, we demonstrate the mechanisms of MTAP-mediated tumor suppression via the utilization of a phospho-RTK antibody array screen and identify IGF1R as a driver pathway in MTAP-deficient RCC." (PMID 30701095, 2019). "IGF-1R-stimulated downstream signaling, in particular, has become a target for inhibition by small molecules or receptor-specific antibodies in multiple tumor types." (PMID 31101650, 2019). "We also found that IGF-1 and IGF-1R expressions correlated with tumor and adenocarcinoma incidence, as well as caecal and fecal pH and β-GA values (p < 0.05)." (PMID 31480481, 2019). "Elevated expression of IGF-1 and IGF-1R correlates with tumour progression, poor prognosis, apoptosis resistance and chemotherapy resistance in several cancer types, including BCa." (PMID 31076571, 2019).
tumor (continued). "Inhibition of IGF-1R by small molecule inhibitor has been shown to prevent tumor growth in mice xenograft models." (PMID 31467485, 2019). "Surprisingly, the Tris DBA-Pd HANP particles alone were more effective than those conjugated to antibodies to IGF1R, and tumor growth appeared to plateau at week three while the other groups continued their exponential growth." (PMID 30824801, 2019). "Combination of GAS5 with gefitinib markedly reduced the levels of phospho-IGF-1R, pEGFR, and the downstream signaling proteins pAKT and pERK, thus inhibiting tumor growth." (PMID 31847392, 2019). "Unlike IGFBP-1 to IGFBP-6, IGFBP-7 inhibits the proliferation of tumor cells by directly binding IGF1R." (PMID 31661774, 2019). "This same tumor also had six variants of uncertain significance: ARID2 c.1672C > T p.(R558C), FLT3 c.2546G > A p.(R849H), IGF1R c.3897C > G p.(N1298K), MSH6 c.1157C > G p.(P386R), PBRM1 c.2504G > A p.(R850H), and RNF43 c.1114C > T p.(P372S)." (PMID 31046843, 2019). "In conclusion, cell vaccines overexpressing IGF1R along with other immune stimuli succeeded in breaking the tolerance toward IGF1R, but the obtained immune response only marginally affected tumor onset." (PMID 30979001, 2019). "These and other findings have thus identified IGF1R as a promising therapeutic target in different fusion gene driven neoplasms." (PMID 31426421, 2019). "Tumour lysates extracted from Kitra-SRS xenografts were also investigated for IGF-1R/AKT signalling." (PMID 31676869, 2019). "IGFBP2 is the second most abundant IGF-binding protein (after IGFBP3), functions as a carrier for IGF-1 and likely promotes tumor progression through IGF-1R pathway." (PMID 31399589, 2019). "In the MIA PaCa-2 model, TAE226 inhibited phosphorylation of Y397-FAK and phosphorylation of S473-Akt as IGF-1R signaling in the cell culture in vitro and the tumor in mice." (PMID 31215459, 2019). "It has been demonstrated that IGF-1R signaling is important in tumor growth, development, and its metastasis." (PMID 30041514, 2019). "IGF1R is involved in cell growth and survival and has a crucial role in tumor transformation and survival of malignant cells." (PMID 31660858, 2019). "IGF-1R ASOs were transfected ex vivo into autologous tumor cells that were re-implanted into the subcutaneous tissues, with response in 8/12 patients." (PMID 31416218, 2019). "An intermediate to high staining for IGF2 (82%; median score 5; range 3–6) and IGF1R (65%; median score 4; range 2–6) was observed in most tumor tissues and for IGF2R (median score 5; range 4–6) in all ACCs." (PMID 30838516, 2019). "A critical finding is that miR-9, as a tumor-suppressive microRNA, operated through the IGF1R pathway to regulate the targeting of cyclin B1 and N-cadherin and the upregulation of E-cadherin in CRC cells in the HG-concentration medium." (PMID 30965609, 2019). "In colon cancer, let-7e led to a significant reduction IGF-1R protein level and downstream Akt inhibition to suppress tumor growth." (PMID 31847392, 2019). "To assess the impact of our treatments on IGF1R expression, we used IHC to stain the tumor xenografts with antibodies against IGF1R." (PMID 30824801, 2019). "Previous studies have reported that the IGF-I/IGF-1R axis plays a role in tumor development and progression." (PMID 31467485, 2019). "IRA has a higher affinity for IGF2 compared with the IGF1R and its expression in malignant tumor tissue has been suggested to be involved in cancer development." (PMID 30838516, 2019).
tumor (continued). "Screening of a personalized PDX model with a selection of anticancer drugs revealed that one of the most effective agents was the IGF1R antibody figitumumab which induced significant tumor growth inhibition (76%) compared to untreated controls." (PMID 31426421, 2019). "Istiratumab monotherapy led to tumor stasis, whereas the combination of dual IGF-1R/ErbB3 inhibition with chemotherapy resulted in tumor regression for all three combinations." (PMID 31728045, 2019). "On the other hand, the data presented here is mainly obtained from cell lines; the role of TSN on IGF-1R and the involved cell signaling warrant an investigation in tumor animal models treated with TSN in the future." (PMID 30213025, 2018). "Several small molecule tyrosine kinase inhibitors against IGF-1R inhibited tumor growth in vivo model." (PMID 29531225, 2018). "The ORs for IGF1R and p-mTOR additionally adjusted for grade, tumor size and positive lymph node status were respectively 2.32 (95%CI:1.02–5.30; p = 0.05) and 2.58 (95%CI:0.97–6.81; p = 0.06)." (PMID 29486734, 2018). "The IGF-1R is overexpressed in many tumors, making the proto-oncogene transcription and translation, and promoting tumor cell growth." (PMID 29455664, 2018). "High expression of IGF-1R due to phosphorylated activity of IRS-1 can enhanced activity of ER-α which leads the tumor towards metastasis." (PMID 29787591, 2018). "miR-130a- and miR-145-targeted molecular networks including TGFβ and IGF1R pathways were correlated with higher tumor stages in cancer patients." (PMID 29973593, 2018). "In fact, IGF-1R expression is correlated with higher tumor grade, and its co-expression with epidermal growth factor receptor (EGFR) was shown to be be significantly associated with poor survival in PDAC." (PMID 29475434, 2018). "In particular, miR-14015 and miR-19516 decrease tumour growth and metastasis through proliferative delay or arrest by targeting IGF-1R in NSCLC." (PMID 29712908, 2018). "The significant up-regulated expression of IGF-1R is increased by the suppression of TSGs which lead tumor towards metastasis." (PMID 29787591, 2018). "The tumour suppressive TAp63 isoforms negatively control Igf1r transcription, whereas Igfbp3 is a target of transcriptional repression by ΔNp63." (PMID 30594912, 2018). "Alterations in cytokine and chemokine production in the tumor epithelium as a result of attenuated IGF-1R signaling suggests changes in immune cell recruitment to the primary tumor." (PMID 30458886, 2018). "Taken together, IGF-1R plays a vital role in cellular proliferation and tumor growth and aberrantly expressed in multiple cancers." (PMID 29861465, 2018). "Studies performed on IGF1R tissue expression, showed that tumor expression was significantly higher than in the surrounding tissue and correlated with the HCC differentiation and cirrhosis, but not to the number or size of tumors, HBV infection, and AFP level." (PMID 29702590, 2018). "We further demonstrated that IGF1R regulates tumor cell proliferation in IGROV1 cells, whereas in OAW42, it determines autophagy as well." (PMID 30237504, 2018). "We then performed qRT-PCR in a set of 30 primary GC tissues and 30 paired non-tumor gastric tissues from the same patients and found that IGF-1R was upregulated in GC tissues." (PMID 29973668, 2018). "Administration of IGF1R-selective inhibitors (A12) reduced IGF1-induced effects and was associated with a significant reduction of HCC tumor growth." (PMID 29702590, 2018). "In human hepatocarcinogenesis, overexpression of the secreted ligand IGF-II is of special importance for tumor formation and activation of the relevant receptor IGF-1R correlates with poor patient prognosis." (PMID 30733684, 2018). "In this study, we revealed a novel role for IGF-1R as a suppressor of tumorigenesis by regulating the tumor microenvironment through protecting tumor epithelial cells from EnR stress." (PMID 30458886, 2018).
tumor (continued). "Male Balb/CAnNcrj-nu mice of 4 weeks old were implanted with 5 × 106 of A549 cells (NSCLC cells line with overexpression of IGF-1R) in 100 μL medium and allowed to grow tumor size about 400 mm3." (PMID 29861465, 2018). "The signaling of IGF1R plays a role in tumor cell motility and adhesion; thus, it contributes to tumor spreading and metastasis." (PMID 30237504, 2018). "To further explore the role of IGF1R in the tumor cells’ response to GDC0032, we examined the morphology of tumor cells after treatment with GDC0032 over time." (PMID 30237504, 2018). "IGF-1R inhibition in tumor epithelial cells elevated interleukin (IL)-6 and C-C motif chemokine ligand 2 (CCL2) expression, which was reversed by ROS scavenging." (PMID 30458886, 2018). "Currently available clinical data on anti-IGF-1R therapies have demonstrated that these targeting approaches can promote strong antitumor activities in several tumor types; however, the efficacy is likely to be limited to a small patient subset." (PMID 30231881, 2018). "IGF-1R specific siRNA (0.125 μg/mm3 of tumor volume) expressing plasmids with polyethyleneimine (PEI) 3 μL/μg and negative control siRNA at a same dose were injected intratumorally 4 times every 5 days." (PMID 29861465, 2018). "The PDAC hypoxic tumor microenvironment also induced the production of IGF1 by cancer-associated fibroblasts (CAFs) and the expression of IGF1R in PDAC cells." (PMID 30366466, 2018). "Lastly, miR-130a and miR-145 mimics, as well as IGF1R inhibitor NT157 improved anti-tumor immunity and inhibited metastasis in preclinical mouse models." (PMID 29973593, 2018). "When inhibition of CAV1 or IGF1R was applied, it corrupted the complex allowing apoptotic molecules to resume mitigating tumor development." (PMID 30042829, 2018). "By inhibiting Insulin-Like Growth Factor-1-Receptor (IGF-1R) signaling, Klotho (KL) acts like an aging- and tumor-suppressor." (PMID 30441794, 2018). "In HNSCC, IGF1R overexpression is associated with adverse survival, HPV negativity and high tumour T-stage." (PMID 30594912, 2018). "In PDAC, cancer-associated fibroblasts produce IGF-1 under hypoxic conditions and promote tumor cell migration via IGF-1R signaling under hypoxia in vitro." (PMID 29475434, 2018). "Patients with higher coffee consumption had lower tumor IGF1R levels (P = 0.025), but only among the normal-weight patients (P = 0.005)." (PMID 29928262, 2018). "Inhibiting IGF-1R in either mouse or human tumor epithelial cells increased reactive oxygen species (ROS) production and activation of the endoplasmic reticulum stress response." (PMID 30458886, 2018). "To further explore that miR-99b-5p and miR-203a-3p inhibited tumor progression through targeting IGF-1R, we constructed rescue experiments and co-transfected of si-IGF-1R and anti-miR-99b-5p/203a-3p or their controls in GC cells." (PMID 29973668, 2018). "Third, tumor cells can increase expression of alternative RTKs such as IGF1R in order to bypass HER2 inhibition and maintain intracellular signaling flux." (PMID 30323337, 2018). "Increased MMP secretion and activity in tumors with attenuated IGF-1R suggests there is active tumor stroma matrix remodeling." (PMID 30458886, 2018). "We previously demonstrated that the IGF-1R acts as a tumor and metastasis suppressor in the Wnt1 mouse model of TNBC." (PMID 30458886, 2018). "In many studies phosphorylation of IGF1R was inhibited, which reduced Akt activation, enhanced cancer cell apoptosis, and suppressed tumor cell growth." (PMID 30013477, 2018). "IGF1R is frequently overexpressed in tumors such as thyroid, colorectal, prostate, breast, and ovarian, and regulates tumor cell proliferation and survival via apoptotic signaling." (PMID 30237504, 2018).